SLC6A5 (solute carrier family 6 member 5)
Description:
Sodium- and chloride-dependent glycine transporter. Terminates the action of glycine by its high affinity sodium-dependent reuptake into presynaptic terminals. May be responsible for the termination of neurotransmission at strychnine-sensitive glycinergic synapses. [Isoform 2]: Lacks sodium- and chloride-dependent glycine transporter activity. [Isoform 3]: Lacks sodium- and chloride-dependent glycine transporter activity.
Synonyms: GlyT-2; GlyT2; NET1; HKPX3
Tractability: Small molecule: a high-quality ligand is known; it belongs to a druggable protein family. Antibody: UniProt places it where antibodies can reach, with high confidence; its Gene Ontology location is reachable by antibodies, with high confidence; UniProt predicts a signal peptide or a membrane-spanning region. PROTAC: a small molecule that binds it is known.
Target class: SLC superfamily of solute carriers; SLC06 neurotransmitter transporter family; Electrochemical transporter; Transporter
Safety:
Unwanted effects reported when the protein is acted on. In parentheses: how it was acted on, where the effect was seen, and who reports it.
rapid rise of motor side effects at the beginning of the treatment (source: ClinPGx)
Gene: Protein-coding gene on chromosome 11 (20,599,594 to 20,659,285, forward strand). Ensembl gene ENSG00000165970.
Subcellular location: Cell membrane
Pathways (Reactome):
Disease: Defective SLC6A5 causes hyperekplexia 3 (HKPX3)
Transport of small molecules: SLC-mediated transport of neurotransmitters
Gene Ontology:
Molecular function: glycine:sodium symporter activity; transmembrane transporter activity
Biological process: glycine import across plasma membrane; synaptic transmission, glycinergic; chemical synaptic transmission; neurotransmitter transport; sodium ion transmembrane transport
Cellular component: plasma membrane; dense core granule; endosome; membrane; synapse
Genetic constraint (gnomAD): Loss-of-function variants: 47 observed, 79.14 expected, observed/expected ratio (o/e) 0.59, 90% interval 0.47 to 0.76. The upper end of that interval is the gene's LOEUF score, 0.76, which puts it in group 3 of 6, group 1 being the genes least tolerant of losing a copy. Missense variants: 962 observed, 984.06 expected, observed/expected ratio (o/e) 0.98, 90% interval 0.93 to 1.03. Synonymous variants: 419 observed, 393.67 expected, observed/expected ratio (o/e) 1.06, 90% interval 0.98 to 1.15.
Gene-disease validity (ClinGen):
ClinGen rates the evidence that SLC6A5 causes each of these diseases.
hyperekplexia 3 (autosomal recessive): Definitive. Any hereditary hyperekplexia in which the cause of the disease is a mutation in the SLC6A5 gene.
Homologues: Orthologues: chimpanzee SLC6A5 (99% identical), macaque SLC6A5 (99% identical), rabbit SLC6A5 (96% identical), pig SLC6A5 (96% identical), rat Slc6a5 (95% identical), mouse Slc6a5 (93% identical), dog SLC6A5 (91% identical), guinea pig SLC6A5 (88% identical), tropical clawed frog slc6a5 (77% identical), zebrafish slc6a5 (69% identical), Caenorhabditis elegans snf-6 (29% identical). Paralogues in human: SLC6A14 (40% identical), SLC6A7 (39% identical), SLC6A9 (37% identical), SLC6A13 (34% identical), SLC6A12 (34% identical), SLC6A6 (32% identical), SLC6A11 (32% identical), SLC6A3 (32% identical), SLC6A8 (32% identical), SLC6A2 (32% identical), SLC6A4 (30% identical), and 6 more.
Diseases named in the same sentence as SLC6A5 in open-access papers:
SLC6A5 is named in the same sentence as 28 diseases in open-access papers, as found by Europe PMC text mining. Sharing a sentence is not in itself a finding about the gene and the disease. The quoted sentences say what the papers report.
hyperekplexia (30 papers, 2008 to 2025). "Pathogenic variants in human SLC6A5 result in hyperekplexia characterized by exaggerated startle response and life-threatening apneas that can result in sudden death in infancy." (PMID 38862622, 2024). "In one (2%) of 43 infants (case 099), the genetic diagnosis led to a new clinical diagnosis: an infant initially diagnosed with clinical seizures was also diagnosed with hyperekplexia after detection of a SLC6A5 variant." (PMID 37596007, 2023). "In the instance of the glycine transporter 2 (GLYT-2, SLC6A5), several mutations have been linked to hyperekplexia/startle disease." (PMID 35295842, 2022). "In humans, homozygous or compound heterozygous recessive inheritance carriers of various missense, nonsense, and frameshift GlyT2 (SLC6A5) mutations display hyperekplexia, a paroxysmal neurological disorder caused by impaired glycinergic neurotransmission." (PMID 34200954, 2021). "The remaining gene slc6a5 encodes a glycine transporter protein whose loss of function is implicated in human hyperekplexia." (PMID 32211332, 2020). "One developed seizures at 33 hours of age, and was later diagnosed with hyperekplexia, confirmed by a homozygous novel missense mutation SLC6A5 (case 3; online supplementary eTable 2)." (PMID 30425113, 2019). "In a previous report, asymptomatic parents of multiple patients with SLC6A5-related hyperekplexia have been observed with truncating variants, which is in line with our observation." (PMID 31604777, 2019). "Hyperekplexia patients with a benign phenotype and variants in SLC6A5 are significantly less likely to have recurrent infantile apnea than those with GLRA1 variants." (PMID 31604777, 2019). "If—as in this case—a variant in SLC6A5 is revealed to cause the disease, the patient is expected to have a benign form of hyperekplexia." (PMID 31604777, 2019). "Mutations in Slc6a5 cause hyperekplexia, a neurological disorder with pronounced startle responses and neonatal apnea." (PMID 29943428, 2018). "Mice in which GlyT2 has been deleted develop a fatal hyperekplexia phenotype during the second postnatal week and mutations in the human gene encoding GlyT2 (SLC6A5) have been identified in patients with hyperekplexia." (PMID 29055035, 2017). "SLC6A5 is a glycine neurotransmitter transporter implicated in hyperekplexia, a neuromotor disorder." (PMID 24651125, 2014). "Genetic analysis of hyperekplexia patients has identified mutations in the human GlyT2 gene (SLC6A5) as the second most common cause of the disease, after mutations affecting the glycine receptor and other key proteins in glycinergic synapses." (PMID 23650557, 2013). "Mutations in SLC6A5, encoding GlyT2, cause hereditary hyperekplexia in humans, and similar phenotypes in knock-out mice, and variants are associated with schizophrenia." (PMID 22272310, 2012). "SLC6A5 (P = 3.0×10−4) is associated with hyperekplexia, a neurological disorder characterized by an excessive startle response." (PMID 18670650, 2008). "The diagnosis altered the patient's medical care to his benefit because SLC6A5 mutations with rather benign courses of hyperekplexia may be spared of needless pharmacotherapy." (PMID 31604777, 2019). "Our results contribute to the elucidation of the mechanisms underlying the dynamic trafficking of this important neuronal protein which has pathological relevance since mutations in the GlyT2 gene (SLC6A5) are the second most common cause of human hyperekplexia." (PMID 23484054, 2013). "Thus, we suggest that a rather benign course of hyperekplexia with SLC6A5 mutations may render a continuous pharmacotherapeutic management dispensable." (PMID 31604777, 2019). "One patient (SLC6A5) was commenced on clonazepam for gene-related hyperekplexia and referred to specialist neurologist for advice." (PMID 40399560, 2025).
hyperekplexia (continued). "The most severe clinical manifestations result from mutations in SLC6A3, SLC6A5, SLCA18, and SLCA19 giving rise to infantile dystonia and parkinsonism (5, –, 7), hyperekplexia (9, –, 11), and Hartnup disease (45, –, 47), respectively." (PMID 25202009, 2014). "Although seizures are not a prominent feature of hyperekplexia, the strong association of SLC6A5 with paroxysmal apneas suggests the possibility of enhanced SUDEP risk in the context of pre-existing epilepsy." (PMID 38862622, 2024). "Therapeutic management in hyperekplexia might include medication with an allosteric potentiator of the inhibitory GABAA receptor clonazepam in patients with variants in GLRA1 and SLC6A5." (PMID 31604777, 2019). "In addition to mutations in the genes GLRB (encodes glycine receptor β-subunit), SLC6A5 (encodes glycine transporter 2) and GPHN (encodes the integral membrane protein gephyrin), mutations in the gene GLRA1 (encodes the α1-subunit of the GlyR) account for 40 - 80% of hyperekplexia." (PMID 23006332, 2012). "In addition, human heterozygous carriers of SLC6A5 mutations do not express hyperekplexia." (PMID 34200954, 2021). "Patients diagnosed with startle disease/hyperekplexia do not always carry mutations in the known associated disease genes (GLRA1, GLRB, SLC6A5)." (PMID 37903619, 2023).
startle disease (8 papers, 2011 to 2023). "More recently, a presynaptic component to this disease has been demonstrating with missense, nonsense, and frameshift mutations identified in the glycine transporter GlyT2 gene, SLC6A5 (hyperekplexia 3)." (PMID 31878022, 2019). "Sequencing of other candidate genes affected in startle disease excluded further pathogenic sequence variations, as only common single nucleotide variants were found (Glrb: exon 5, c.A555G, p.L163L, rs13477223; SLC6A5: exon 2, c.A109G, p.T37A, rs31048165)." (PMID 28724750, 2017). "Of the clinical laboratories world-wide offering screening for startle disease, seven screen for GLRA1 mutations, three offer screening for GLRB and only one offers screening for SLC6A5 mutations." (PMID 23238346, 2013). "Within our patient cohort several patients diagnosed for startle disease do not carry a mutation in the known common genes, i.e., GLRA1, GLRB, SLC6A5." (PMID 37903619, 2023). "Individuals with startle disease lacking mutations in GLRA1 and SLC6A5 were screened for genetic variation in GLRB coding exons and donor and acceptor splice junctions by Sanger DNA sequencing." (PMID 23238346, 2013).
schizophrenia (5 papers, 2008 to 2025). A major psychotic disorder characterized by abnormalities in the perception or expression of reality. "In particular, we wanted to examine phenotypes relevant to schizophrenia and anxiety given the association between SLC6A5 and NMDA receptors and these conditions in humans." (PMID 22272310, 2012). "The significant association of SNP1 of SLC6A5 with schizophrenia was confirmed in both genotype and allele frequencies in the Full-size Sample Set (P = 0.032, P = 0.018, respectively)." (PMID 18638388, 2008). "The significant association of SNP1 of SLC6A5 with schizophrenia was confirmed in the Full-size Sample Set (P = 0.018)." (PMID 18638388, 2008). "However, the similar spectrum of behavioral changes compared to other schizophrenia mouse models is intriguing considering the association of a SNP near human SLC6A5 with schizophrenia." (PMID 22272310, 2012). "We investigated the association of SLC1A4, SLC1A5, SLC6A5 and SLC6A9 genes with schizophrenia in the Japanese population by analysing total 21 common SNPs." (PMID 18638388, 2008). "We observed significant associations with schizophrenia in combinations of SNP2-SNP7 of SLC1A4 (P = 0.037) and SNP1-SNP4 of SLC6A5 (P = 0.043)." (PMID 18638388, 2008). "No report to date has indicated an association between slc6a5 gene expression and the appearance of anxiety-like behavior; however, mice with slc6a5 homozygous or heterozygous defects exhibit grooming and hyperactive behaviors that are typically observed in mouse models of schizophrenia." (PMID 28650979, 2017). "We conclude that at least one susceptibility locus for schizophrenia is located within or nearby SLC6A5, whereas SLC1A4 SLC1A5 and SLC6A9 are unlikely to be major susceptibility genes for schizophrenia in the Japanese population." (PMID 18638388, 2008). "We concluded that at least one susceptibility locus for schizophrenia may be located within or nearby SLC6A5, whereas SLC1A4, SLC1A5 and SLC6A9 are unlikely to be major susceptibility genes for schizophrenia in the Japanese population." (PMID 18638388, 2008). "Recently, negative associations of schizophrenia with polymorphisms in SLC6A9 and SLC6A5 were reported in the Chinese and the German population, respectively." (PMID 18638388, 2008). "There has been no linkage with schizophrenia reported to the chromosome regions where SLC1A5, SLC6A5 or SLC6A9 are located." (PMID 18638388, 2008).
depression (4 papers, 2016 to 2023). "In the current work, we focus on examining the association of the SLC1A2 rs4354668, SLC6A9 rs2486001, and SLC6A5 rs2000959 polymorphisms with major depressive disorder and its clinical variables in the Polish population." (PMID 36233781, 2022).
epilepsy (4 papers, 2020 to 2025). A brain disorder characterized by episodes of abnormally increased neuronal discharge resulting in transient episodes of sensory or motor neurological dysfunction, or psychic dysfunction. "Nav2, Ptpn5, Ldha, and Dbx1 are deemed higher priority as they have a direct biological association with seizures or epilepsy, while Prmt3 and Slc6a5 have an indirect association." (PMID 38862622, 2024). "Many of these genes are associated with epilepsy and ictogenesis, including DPP10, DOCK8, IAH1, LRRC4C, and SLC6A5." (PMID 36506088, 2022). "Of note, many seizure-related genes identified in this study (for e.g. ACBD5, SLC6A5, STUB1) are not included in the routine epilepsy panel (R59) and this highlights the benefit of the gene-agnostic analytic approach offered by the rapid WES testing." (PMID 40399560, 2025).
Obesity (2 papers, 2016 to 2022). Accumulation of substantial excess body fat. "A potential causal role for metabolic differences under similar obesity state was detected for PTPRE, IL-6R and SLC6A5." (PMID 27907186, 2016).
cervical cancer (1 paper, 2016). A primary or metastatic malignant neoplasm involving the cervix. "QMSP was designed for 5 genes (GFRA1, SLC6A5, SOX1, SOX14, TBX20) and their diagnostic potential was evaluated on scrapings from a large series of cervical cancer patients (n=125: 57 ADC and 68 SCC) and controls with similar age." (PMID 27738327, 2016).
developmental delay (1 paper, 2019). "Moreover, patients with variants in GLRB and SLC6A5 are more likely to have a developmental delay than those with GLRA1 variants." (PMID 31604777, 2019).
glycine encephalopathy (1 paper, 2021). Glycine encephalopathy (GE) is an inborn error of glycine metabolism characterized by accumulation of glycine in body fluids and tissues, including the brain, resulting in neurometabolic symptoms of variable severity. "In addition, known glycine transporters such as GlyT1 and GlyT2 encoded by SLC6A9 and SLC6A5, respectively, are associated with glycine encephalopathy." (PMID 33428810, 2021).
Hypertonia (1 paper, 2011). A condition in which there is increased muscle tone so that arms or legs, for example, are stiff and difficult to move. "Individuals with mutations in SLC6A5 present with hypertonia, an exaggerated startle response to tactile or acoustic stimuli." (PMID 21298005, 2011).
prostate carcinoma (1 paper, 2016). A carcinoma that arises from epithelial cells of the prostate gland. "So far, methylation of SLC6A5 (also known as the glycine transporter gene GLYT2) was associated with glioma, prostate cancer, oral and pharyngeal cancer; and the expression was down-regulated during rat liver regeneration." (PMID 27738327, 2016).
cancer (1 paper, 2016). A tumor composed of atypical neoplastic, often pleomorphic cells that invade other tissues. "In the second diagnostic evaluation 229 scrapings were analyzed for SLC6A5, SOX1, SOX14 and TBX20 hypermethylation using the QMSP threshold values that were set in the normal and cancer samples." (PMID 27738327, 2016). "Except for TBX5, all 5 genes (GFRA1, SLC6A5, SOX1, SOX14 and TBX20) were significantly differentially methylated between normal and cancer tissues with a high methylation frequency in both ADC and SCC." (PMID 27738327, 2016).
tumor (1 paper, 2020). "Two missense variants (SAA2 and SLC6A5) were heterozygous in blood and homozygous in the tumor and both are located on chromosome 11 in the LOH region." (PMID 33379206, 2020).
SLC6A5 also shares sentences with these, for which no sentence is quoted: Apnea (3 papers); Anxiety (2); neurological disorder (2); alcohol dependence (1); Dravet syndrome (1); Dystonia (1); Hartnup disease (1); hyperekplexia 3 (1); hyperlipidemia (1); migraine (1); Parkinsonism (1); peripheral neuropathy (1); Seizure (1); ulcerative colitis (1); viral infection (1).